HIF1A (hypoxia inducible factor 1 subunit alpha)
Diseases named in the same sentence as HIF1A in open-access papers (continued):
Sharing a sentence is not in itself a finding about the gene and the disease.
renal carcinoma (continued). "On the other hand, TRIM21 could inhibit glycolysis of renal cancer cells by degrading HIF-1α to hinder tumor progression." (PMID 40998798, 2025). "Interestingly, there is evidence that PGC-1α is suppressed by HIF-1α in renal cancer cells and hepatocytes." (PMID 40713487, 2025). "Melatonin could antagonize HIF-1α-controlled aerobic glycolysis through ROS scavenging and synergistically inhibit cell growth with sunitinib in renal carcinoma cells by reversing the Warburg effect." (PMID 39588377, 2024). "Our finding provided further resolution to a longstanding question: why does destruction of HIF-1α in VHL-deficient renal cancer cells not occur during chronic hypoxia." (PMID 37777750, 2023). "The present study aimed to determine HIF1A mRNA expression, the protein expression of HIF-1α and VEGF-A in the three most common histological types of renal cancer – ccRCC, pRCC, chRCC, as well as to analyze HIF1A and VEGFA differential gene expression and its influence on patient’s survival." (PMID 38053655, 2023). "HIF-1α protein is overexpressed in solid malignant tumours including breast, colon, gastric, lung, skin, ovarian, pancreatic, prostate, and renal carcinomas when compared to their respective normal tissues; consistent with the idea that HIF-1α is upregulated during cancer progression." (PMID 36879003, 2023). "Deletion of the von Hippel-Lindau (VHL) tumor suppressor gene in renal cancer cells leads to the accumulation of HIF-1α and an increase in Clut2 expression, which promotes aerobic glycolysis in renal cancer cells and leads to metabolic reprogramming of renal cancer cells." (PMID 35251009, 2022). "The inhibition of renal cancer induced by hZIP1 might be connected with HIF-1α (Zn2+ might act as an intermediary) and even metabolic changes, which requires further investigation." (PMID 34926261, 2021). "To confirm further that HIF-1α might serve as a tumor promoter in renal cancer, we examined its function in a xenograft tumor model (nude mice)." (PMID 34926261, 2021). "However, some studies held opposing views; they considered HIF-1α to act as a tumor suppressor to inhibit cancerous behavior in renal cancer." (PMID 34926261, 2021). "Studies have suggested that E-cadherin regulated HIF1α, which may be one of the mechanisms by which renal cancer exosomes promote vascular permeability." (PMID 34179017, 2021). "Likewise, overexpression of lncRNA-SNHG12 weakens the miR-199-5p-mediated suppression of hypoxia-inducible factor 1 alpha (HIF1α), supporting anchorage-independent growth, cell survival, and invasion in vitro and the in vivo growth of renal cancer." (PMID 33435156, 2021). "Such as the degradation of HIF‐1α and ZHX2 can be inhibited in VHL deficiency renal carcinoma." (PMID 32780537, 2020). "Moreover, Hif-1α and Hif-2α have different physiological roles: for example, renal cancer cell growth is retarded and enhanced by Hif-1α and Hif-2α, respectively." (PMID 32290638, 2020). "Furthermore, inhibition of HDAC6 in Vhl–/– human renal carcinoma cells led to reduced HIF-1α expression and activity." (PMID 32984302, 2020). "We investigated whether TQ is sufficient to suppress HIF-1α activity, and what is its molecular mechanism of action in hypoxic renal cancer cells." (PMID 30832444, 2019). "Consistent with previous study that suggested miR-199a-5p negatively and post-transcriptionally regulated HIF1α in brain tissue of patients with intractable epilepsy, here we consolidated this regulatory axis in renal carcinoma which was further subjected to SNHG12 competition." (PMID 31114448, 2019). "Our data uncovered a crucial role of SNHG12-miR-199a-5p-HIF1α axis in human renal cancer." (PMID 31114448, 2019). "HIF-1A promotes the amplitude of PER2 rhythms in renal cancer." (PMID 31014368, 2019).
renal carcinoma (continued). "However, a separate study showed that shRNA-mediated silencing of both HIF-1α and HIF-2α in pVHL deficient renal carcinoma cells suppressed MXI1 expression, leading to increased C-MYC-dependent PGC-1α expression, and increased mitochondrial biogenesis." (PMID 30767037, 2019). "Renal carcinoma cell lines and tumors produce both HIF-1α and HIF-2α or HIF-2α alone." (PMID 29560117, 2018). "Furthermore, at least in a model of renal carcinoma, HIF1α can repress the expression of PGC-1α (peroxisome proliferator-activated receptor gamma, coactivator-1α), a central regulator of mitochondrial biogenesis, which in turn stabilizes HIF1α." (PMID 30197878, 2018). "However, HIF-1α represses mitochondrial biogenesis/function and oxygen consumption in renal carcinoma cells by inducing pyruvate dehydrogenase kinase 1 or inhibiting the C-MYC/PGC-1β axis." (PMID 30153269, 2018). "However, the role of HIF1α in oncogenesis is poorly elucidated: this protein was found to suppress tumors under certain conditions, although deletions in the HIF1A gene were detected in renal carcinomas." (PMID 28187001, 2017). "The opposing effects of HIF1α and HIF2α in renal cancer could be the result of their different effects on Myc activity." (PMID 26743088, 2016). "STAT3 also inhibits HIF-1α degradation through competition with Von Hippel-Lindau tumor suppressor (pVHL) for binding to HIF-1α, thus stabilising HIF-1α protein levels in tumor cells, and p-STAT3 is a potential regulator of HIF-1α-mediated VEGF expression in renal carcinoma cells." (PMID 26501341, 2015). "This suggested that both BMAL1/CLOCK and HIF1α may be related to the circadian expression of Per2 in renal cancer cell lines." (PMID 25333958, 2014). "However, further investigation is required to determine the molecular mechanisms of HIF1α-induced enhancement of Per2 circadian rhythms and differences between Caki-2 and other renal cancer cell lines." (PMID 25333958, 2014). "Among the biomarkers analyzed, CA 15-3 seems to be a new potential therapeutic target for patients with RCC, considering that this protein affects the invasive behavior of renal cancer cells and is directly regulated by HIF1α, which is the main signaling pathway in RCC carcinogenesis." (PMID 24692843, 2014). "Exactly how HIF stimulates reductive carboxylation remains unclear, but studies of HIF-α knock-down in pVHL-defective renal carcinoma cells demonstrate dependence on HIF-1α and/or HIF-2α, leading to a reduction in intracellular citrate levels." (PMID 24491179, 2014). "STAT3 is required for HIF-1α activation in human renal carcinoma cells and in female MSCs." (PMID 25401104, 2014). "HIF-1α was found to be overexpressed in 13 of 19 tumor types compared with the respective normal tissues, including colon, breast, gastric, lung, skin, ovarian, pancreatic, prostate, and renal carcinomas." (PMID 20003271, 2009). "Therefore, we explored whether HIF-1α/VEGFA/VEGFR signaling pathway influences the process by which AUY922 in-creases renal cancer sensitivity to sunitinib." (PMID 39149033, 2024). "Regarding the relationship between TQ and HIF-1α, TQ can promote the apoptosis of renal cancer cells through the HIF-1α-mediated glycolysis pathway, and its mechanism may be related to the inhibition of ubiquitination and heat shock protein 90 to reduce HIF-1α stability." (PMID 37324458, 2023). "Therefore, the obstructive hydrocephalus caused by CP may be related to the lack of HIF-1α promoting tumor growth, like the tumor suppressor effect of high HIF-1α expression in renal cancer." (PMID 36091021, 2022). "HIF-1α is frequently upregulated in renal cancer, which might be correlated with poor prognosis." (PMID 32047543, 2020). "Nonetheless, additional evidence indicates that in specific tumor contexts such as in renal cancer HIF-1α may also play tumor suppressive functions, thus indicating that the clinical application of pre-clinical studies with HIF inhibitors should be carefully planned." (PMID 27447550, 2016).
renal carcinoma (continued). "For instance, in renal cancer, SAT2 has been shown to enhance cisplatin sensitivity under hypoxia by degrading HIF-1α, suggesting a conserved tumor-suppressive mechanism that warrants further cross-cancer comparisons." (PMID 41150820, 2025). "It would also be of value to explore the interaction of PIEZO1 with known renal cancer drivers, such as VHL, HIF-1α, or mTOR, and to assess its impact on angiogenesis, metabolic regulation, and immune cell infiltration." (PMID 40724850, 2025). "Some studies have shown that CA suppressed hypoxia-induced STAT3 phosphorylation (in Y705), nuclear translocation of STAT3, HIF1α induction, and VEGF expression in human renal cancer cells." (PMID 40493253, 2025). "Using Western blot analysis, we investigated the effect of AUY922 on the HIF-1α/VEGFA/VEGFR pathway by assessing the protein expression levels of HIF-1α, VEGFA, VEGFR1, and VEGFR2 in renal cancer cells." (PMID 39149033, 2024). "The same authors also showed that the immunomodulatory drug fingolimod, by mediating a sustained internalization and degradation of S1P1, abolished HIF-1α and HIF-2α protein expression in renal carcinoma cells." (PMID 35682566, 2022). "Following the example of HIF-1α, HIF-2α can also prevent ROS overload and protect renal carcinoma cells from irradiation-induced cell killing." (PMID 34539584, 2021). "The same authors further showed that FTY720 abolished HIF-1α and HIF-2α protein expression in renal carcinoma cells by downregulating S1P1." (PMID 34502385, 2021). "Chronic hypoxia (72h, 1% O2) actually modifies mitochondria morphology through a mitochondria fusion excess mediated by a HIF-1α, Mitofusin I, BNIP3, and BNIP3L dependent way in several cancer cell types (i.e., colon, lung, cervix, renal cancer cells)." (PMID 34539584, 2021). "Thus, the inhibition of HIF-1α expression may become a promising approach to treat renal cancer." (PMID 32047543, 2020). "Previously, HIF-1α was supposed to be a key oncogenic factor, but recent evidence showed HIF-2α was a predominant driver in renal cancer progression (Keith, Johnson & Simon, 2011)." (PMID 33088626, 2020). "In summary, here we identified the oncogenic property of SNHG12 via miR-199a-5p-HIF1α pathway, which contributed to our comprehensive understanding of the hypoxia response in VHL-proficient renal carcinoma." (PMID 31114448, 2019). "In particular, HIF-1α exclusively regulates glycolytic gene expression, whereas HIF-2α has been shown to promote tumor growth in a renal carcinoma xenograft model and invasiveness (through up-regulation of MMP-2, MMP-9, and PAI-1)." (PMID 31817100, 2019). "STAT3 phosphorylation has been shown to affect HIF-2α levels in 786-O cells and HIF-1α and HIF-2α in Caki-1 renal cancer cells, and STAT3 phosphorylation at Tyr705 and Ser727 residues is increased in ccRCC tumors." (PMID 29464030, 2018). "HIF-1α and HIF-2α are known to reciprocally influence each other concerning VEGF expression and in renal cancer, VEGF secretion particularly is regulated by HIF-2α." (PMID 28903416, 2017). "786-O and RCC10 renal carcinoma cell lines with manipulated levels of VHL, HIF-1α, or HIF-2α were subjected to cellular stresses and analyzed by western blotting for the abundance of apoptotic markers." (PMID 25729330, 2015). "DEC1 was recently identified as hypoxically induced in cDNA microarray studies of the human renal carcinoma cell line RCC4, to be regulated through hypoxia-inducible factor (HIF)-1α and via HIF-1α, able to block adipocyte differentiation." (PMID 15328513, 2004). "It’s important to note that the correlation between HIF-1α and tumor size is not uniform across all renal cancer subtypes or other types of solid tumors." (PMID 38053655, 2023). "Thymoquinone reduces HIF-1α protein levels in renal cancer cells but does not affect HIF-1α protein levels when combined with the proteasome inhibitor MG132." (PMID 37843642, 2023).
renal carcinoma (continued). "Furthermore, ZSTK474 exhibited antiangiogenic activity via downregulating HIF-1α and VEGF, and suppressed renal cancer growth in a xenograft model." (PMID 35918352, 2022). "One of its subunits, HIF-1α is regulated at a protein level by the factor-inhibiting HIF (FIH), which promotes renal cancer cell proliferation by protecting cells from HIF-1α-mediated apoptosis, suggesting that HIF plays contradictive roles in the regulation of cell death." (PMID 35682876, 2022). "This is evident from our observation demonstrating that hypoxia increased chemotactic migration of renal cancer cells but the stabilization of HIF-1α in response to CoCl2 did not." (PMID 33122751, 2020). "Recently, studies showed that HIF-2α, rather than HIF-1α, was a predominant driver in renal cancer progression (Keith, Johnson & Simon, 2011)." (PMID 33088626, 2020). "Renal carcinoma cell line (RCC) 4 lacks wild-type pVHL and expresses both HIF-1α and HIF-2α." (PMID 30903204, 2019). "It has been demonstrated that PKM2 hydroxylation is crucial to HIF-1α transactivation in VHL-null RCC4 renal carcinoma cells at 1% O2 but not at 0.1% O2 levels." (PMID 30216369, 2018). "The present study has shown for the first time that Zn2+ induces expression of HIF1α and HIF2α but not HIF3α in the renal cancer cell line ACHN and the immortalized normal tubular cell line HK-2." (PMID 28686686, 2017). "And PIG3 knockdown mediated by RNAi could up-regulate VEGF secretion via HIF-1α to promote renal cancer cell migration, which contributes to improve our knowledge of PIG3 function and HIF-1α regulation." (PMID 27029070, 2016). "The renal cancer cell line 786-O fails to express HIF-1α under hypoxia but constitutively expresses HIF-2α even under normoxia." (PMID 27373565, 2016). "Since many of the HIF-1 target genes can promote cell survival under hypoxic conditions, it is not surprising that HIF-1α is often overexpressed in various cancers, including breast, lung, pancreatic and renal cancer." (PMID 24925080, 2014). "But, this Oct4 inducing effect appears to be specific for HIF-2α, because HIF-1α does not induce Oct4 in renal carcinoma cells." (PMID 22821840, 2012). "In agreement, endogenous HIF-1α protein levels were not downregulated by zinc in the RCC4 VHL-null renal carcinoma cells either in aerobic condition nor following cobalt treatment." (PMID 21179202, 2010). "Apart from its interaction with HIF1α, PHD3 has also been suggested to hydroxylate other targets, e.g., those involved in the glucose metabolism pathway, regulating their availability, as shown in other models, e.g., human renal carcinoma cells and mice hepatocytes." (PMID 40003076, 2025). "In addition to HIF-1α, however, ANGPTL4 had also been confirmed as a conventional hypoxia-driven proangiogenic factor in renal cancer cells and this process could induced by PPAR signal pathway." (PMID 36407113, 2022). "However, according to the preclinical studies, Thymoquinone destabilizes the binding between HIF-1α and HSP90 and helps in pVHL-mediated polyubiquitination of HIF-1α protein, which is independent of prolyl hydroxylation in renal cancer cells." (PMID 36014432, 2022). "To confirm the selective involvement of HIF-2α, but not that of HIF-1α, in the H19 downregulation, we evaluated changes in the H19 response to combined treatment in the VHL-deficient renal carcinomas cells (786-O) that express endogenous HIF-2α, but not HIF-1α." (PMID 31426484, 2019). "The same effect could also be observed in the cell line 786-O, a renal cancer cell line that only expresses HIF2α and not HIF1α." (PMID 26148512, 2015). "In contrast to this previous observation that HIF-1α does not bind to the Oct4 promoter in renal carcinoma cells, our data show that HIF-1α decreases Oct4 expression and indeed binds to the Oct4 promoter, which was confirmed in two different mESC lines, E14 and C57." (PMID 22821840, 2012).
renal carcinoma (continued). "Many sources give evidence that HIF-2α, and not more intensively studied HIF-1α, acts as regulator in VHL-defective renal carcinomas." (PMID 29560117, 2018). "Second, we examined Hif-1α protein levels by western blot in a number of renal cancer cell lines (ACHN, UO-31 and HK2) and did not detect any change in the amount of Hif-1α when BHLHE41 was overexpressed or knocked down by siRNA." (PMID 27384883, 2016). "Notably, the negative correlation between miR-199a-5p and HIF1α and positive correlation between SNHG12 and HIF1α have been characterized in renal cancer patients." (PMID 31114448, 2019). "TQ reduced HIF-1α protein levels in renal cancer cells; however, it did not affect the HIF-1α protein levels in the presence of proteasome inhibitor, MG132, indicating that the reduction effects of TQ on HIF-1α protein are mediated via the ubiquitination-proteasome dependent pathway." (PMID 30832444, 2019).